APOA1 (apolipoprotein A1)
Diseases named in the same sentence as APOA1 in open-access papers (continued):
Sharing a sentence is not in itself a finding about the gene and the disease.
Alzheimer disease (52 papers, 2013 to 2025). A progressive, neurodegenerative disease characterized by loss of function and death of nerve cells in several areas of the brain leading to loss of cognitive function such as memory and language. "On the other hand, treatment with human ApoA1 in a transgenic model of Alzheimer’s disease reduced amyloid accumulation, brain neuronal loss, and neuroinflammatory response, and improved cognitive function." (PMID 41516203, 2025). "In humans, genetic variants in the APOA1 –APOC3–APOA4 cluster has been associated with the risk of Alzheimer disease, polycythemia induced gastric injury, and metabolic syndrome." (PMID 33432064, 2021). "A case–control study found the APOA1 -75 A allele was associated with an increased risk for Alzheimer’s disease." (PMID 24209603, 2013). "The APOA1 -75 A allele was associated with an increased risk for Alzheimer’s disease." (PMID 26537097, 2015). "Interestingly, the Alzheimer disease (AD) subjects carrying ApoE ɛ4 allele had lower ApoA1 levels but higher ApoB levels and there were differences in biomarker levels (e.g., cholesterol, LDL, and ApoB) for each ApoE genotype with reference to ε3ε3 in a UK Biobank study." (PMID 34930329, 2021). "Higher ApoA1 levels correlate with greater brain tissue volumes, which is significant in neurodegenerative conditions like Alzheimer’s disease." (PMID 40822944, 2025). "ApoA1 levels have also been found to be lower in patients with Alzheimer’s disease compared to the control group." (PMID 41516203, 2025). "ApoA1 and HDL cholesterol play an important role in maintaining cerebrovascular integrity and reducing the risk of Alzheimer’s disease by reducing amyloid (Aβ) plaques and Aβ-mediated inflammation in the cerebrovascular system." (PMID 35911688, 2022). "ApoA1 has been found at decreased levels in subjects with a variety of neurodegenerative disorders including in the serum and cerebrospinal fluid of Alzheimer disease, Parkinson disease and DS with gout subjects." (PMID 26752631, 2016). "ApoA1 plays a role in cholesterol transport and has been shown to prevent learning and memory deficits in an Alzheimer’s disease mouse model by attenuating neuroinflammation." (PMID 25061506, 2014). "Furthermore, a correlation has been demonstrated between reduced plasma ApoA1 levels and the occurrence and severity of Alzheimer’s disease." (PMID 41516203, 2025). "Increased serum apolipoprotein A1 levels have been reported in patients with Alzheimer’s disease." (PMID 38167163, 2024). "Recent studies have found that depleted levels of ApoA1 might may a role in the pathophysiology of various neurodegenerative disorders, such as Alzheimer’s disease and depression." (PMID 35479414, 2022). "There might be an important correlation between Alzheimer’s disease and a decrease of ApoA1 levels in plasma." (PMID 32456156, 2020). "Thus, increasing plasma levels of ApoA1/HDL would be a new interesting strategy for the improvement of the cognitive function in Alzheimer’s disease, although a direct evidence of this is still missing." (PMID 32456156, 2020). "Apolipoprotein A1 (APOA1) is a gene of interest that links alcoholism to Alzheimer’s Disease." (PMID 33199776, 2020). "APOA1 has been reported to be involved in many kinds of malignancies and Alzheimer’s disease." (PMID 32530819, 2020). "Recent studies indicate a potential role of ApoA1 in CAA, with particular emphasis on its ability to support the clearance of amyloid from the brain, among others, after ischemia and in Alzheimer’s disease." (PMID 41516203, 2025). "Alzheimer’s disease patients typically have lower plasma HDL cholesterol (HDL-C) and apolipoprotein-A1 (ApoA-I) concentrations than controls, suggesting that a lack of HDL is detrimental." (PMID 35884800, 2022).
Alzheimer disease (continued). "Elucidating the mechanisms of HDL transcytosis across the blood-brain barrier may be significant pathologically as its constituent apolipoprotein ApoA1 has been demonstrated to confer a protective effect against Alzheimer disease (AD)." (PMID 29163190, 2017).
lung carcinoma (43 papers, 2009 to 2025). "Increased APOA1 levels can reduce the risk of lung cancer, but after lung cancer patients with brain metastases, APOA1 levels are up-regulated." (PMID 39763652, 2024). "In our study, the association of ApoA1 with a specific type of cancer mortality was more significantly enhanced in GI cancer mortality than in lung cancer mortality." (PMID 35796324, 2022). "Hereby, APOA1 expression was also inversely associated with cancer risk, which was proved in lung cancer." (PMID 34211824, 2021). "A lung cancer diagnostic panel consisting of APOA1, CO4A, CRP, GSTP1, and SAMP expression levels reached 95% sensitivity and 81% specificity." (PMID 31976313, 2020). "In the Women’s Health Study, an inverse association of HDL cholesterol and/or apolipoprotein A1 with any cancer, colorectal cancer, and lung cancer was observed." (PMID 32998735, 2020). "In the lung, downregulation of Apoa1 was associated with an increased risk of lung cancer." (PMID 28201999, 2017). "APOA1 up-regulation is associated with breast and lung cancer as suggested elsewhere." (PMID 23844025, 2013). "APOA1 has been shown to reduce lung cancer through its immunomodulatory mechanisms and anti-inflammatory characteristics by inhibiting the neo-angiogenesis of lung tumors while also reducing enzymes that enable cancer metastasis." (PMID 38067270, 2023). "These contrasting findings highlights the need for a nuanced approach to researching APOA1 in lung cancer." (PMID 38067270, 2023). "Future research must consider these subtleties to fully elucidate APOA1’s potential as a biomarker and therapeutic agent in lung cancer." (PMID 38067270, 2023). "The increased APOB/APOA1 ratio correlates with a higher incidence of lung cancer in both males and females." (PMID 38067270, 2023). "It is worth to mention that APOA1 was indicated in the recent study to have a prognostic potential to be used in the progression of obstructive pulmonary disease (COPD) to lung cancer." (PMID 35512017, 2022). "The crude incidences of total, GI, and lung cancer mortalities per 1000 person‐years were significantly higher in patients with lower ApoA1 across the groups." (PMID 35796324, 2022). "Investigations also suggested that people with low levels of ApoA1 are more likely to have lung cancer and colorectal carcinoma." (PMID 33336932, 2021). "For instance, transgenic animal models overexpressing human ApoA1 showed decreased tumor development when inoculated with melanoma and lung cancer cells, while ApoA1 knockout had the opposite effect." (PMID 30745873, 2018). "MALDI MS analysis of this spot has identified it as pro-Apolipoprotein A1, similarly detected and reported by an independent group of researchers studying patients with lung cancer." (PMID 19656391, 2009). "It was also found that the rate of oxidative stress is elevated in patients with a higher APOB/APOA1 ratio, adding to the speculation that these apolipoproteins can increase the incidence of lung cancer." (PMID 38067270, 2023). "Studies have shown a loss of APOA1 and APOB expression in lung cancer patients." (PMID 38067270, 2023). "Consequently, Kaplan‐Meier analyses showed significantly higher rates of the cumulative incidences of total, gastrointestinal, and lung cancer mortality in the lowest ApoA1 tertile group compared to those in the highest." (PMID 35796324, 2022). "A progression from COPD to lung cancer was also indicated for TF and for APOA1." (PMID 35512017, 2022). "While there is a substantial number of studies exploring the function of APOA1 in relation to lung cancer, research on the role APOA2 in lung cancer is scarce." (PMID 38067270, 2023). "For instance, promoter regions of Human kallikrein 2(KLK2) in prostate, Apolipoprotein A1 (APOA1) in liver, NK6 homeobox 3 (NKX6.3) in stomach, paired box gene-8 (PAX-8) in kidney, and Surfactant Protein B (SFTPB) in lung cancers were among the selected markers from our pipeline." (PMID 35729208, 2022).
lung carcinoma (continued). "It is evident that APOA1’s role is not uniform across different lung cancer contexts and that its function may be influenced by the underlying pathology of the lung condition." (PMID 38067270, 2023). "Similarly, tumour bearing mice overexpressing ApoA1 had reduced tumour growth and metastasis of melanoma and lung cancer cells compared to mice lacking ApoA1." (PMID 36050733, 2022). "In contrast, NFKBIA, PSME3, SPARCL1, CCL15, and APOA1 did not return established entries under these filters and at the time of query, indicating that, within IPA, they are not currently categorized as clinical lung cancer biomarkers." (PMID 41465234, 2025).
ischemic stroke (40 papers, 2009 to 2026). A stroke disorder caused by obstruction of blood flow to the brain, due to thrombotic (local blood clot formation) or embolic (due to a blood clot or other material traveling from another site) event. "Multivariate regression analysis adjusting for multiple ischemic stroke risk factors showed that the ApoB/ApoA1 ratio had a higher predictive value for ischemic stroke (OR: 2.33, 95% CI 1.80–3.00) than the non-HDL-C/HDL-C ratio (OR: 1.47, 95% CI 1.17–1.86)." (PMID 38274879, 2023). "Current smoking, ApoA1, ApoB, male sex and education level showed stronger associations with CE whereas age was preferentially associated with ischemic stroke." (PMID 34772344, 2021). "Lower levels of APOA1 were found to be correlated with an increased risk of the acute onset of ischemic stroke." (PMID 34702323, 2021). "Among traditional cardiovascular risk factors, apolipoprotein B/apolipoprotein A1 (ApoB/ApoA1) ratio is recognized to have the strongest predictive value for ischemic stroke." (PMID 32017458, 2020). "It was repeatedly demonstrated that elevated ApoB/ApoA1 ratio played a risk role in ischemic stroke." (PMID 32017458, 2020). "A high ApoB/ApoA1 ratio has been considered as risk factors in ischemic stroke, carotid stenosis, and other vascular diseases, which was consistent with our present study in some degrees." (PMID 33614678, 2020). "In summary, the serum total APOA1-UP level was inversely correlated with the presence of ischemic stroke, and APOA1-UP can be used as a diagnostic biomarker for acute ischemic stroke at early stage, with a sensitivity of 90.63% and a specificity of 97.14%." (PMID 27043525, 2016). "Low levels of apolipoprotein A‐I (APOA1) correlate with greater risk of ischemic strokes and neurodegeneration, and lower serum APOA1 levels may contribute to metabolic dysregulation and neuroinflammation following concussions." (PMID 41318967, 2026). "This is supported by findings that elevated ApoA1 levels lower the risk of ischemic stroke, due to its ability to reduce amyloid toxicity and oxidative stress and inhibit neuroinflammatory pathways, which are key mechanisms contributing to vascular health after ischemia." (PMID 41516203, 2025). "Polymorphisms in APOA1, such as rs670, are associated with increased ischemic stroke risk." (PMID 40869228, 2025). "Among these proteins, elevated APOA1 levels reduce the risk of ischemic stroke, may delay the progression of atherosclerotic lesions, and also promote lesion regression." (PMID 36959823, 2023). "BUD13, a subunit of the retention and splicing complex, may significantly increase the risk of ischemic stroke by affecting APOA1 leading to elevated TG and VLDL45,46." (PMID 36720935, 2023). "However, current smoking, ApoB, low ApoA1, male sex and education level of ≤ 9 years of schooling were preferentially associated with CE compared to ischemic stroke." (PMID 34772344, 2021). "Therefore, the serum level of APOA1-UP is a diagnostic biomarker candidate for ischemic stroke in the early stage." (PMID 27043525, 2016). "The increase in ApoB/ApoA1 was positively correlated with the incidence rate of ischemic stroke (the PFDR-values in the analyses of IVW, Weighted median, MR-PRESSO were all significantly less than 0.05)." (PMID 38310324, 2024). "A total of 163 patients aged 70 years were included, and an elevated ApoB/ApoA1 ratio was shown to be an independent predictor of ischemic stroke in people aged 70 years and older in a multivariate regression analysis." (PMID 38274879, 2023). "A graded increase with increased apoB/apoA-1 ratio was also found for ischaemic stroke, CABG or PCI, CV mortality, and MACE and coronary intervention as a combined event." (PMID 34851955, 2021). "ApoA1 was more protective for CE (HRCE 0.81, CI 0.78–0.84) as compared to ischemic stroke (HRst 0.94, CI 0.90–0.98) (p for equal association < 0.001)." (PMID 34772344, 2021).
ischemic stroke (continued). "We therefore performed a case-control study to investigate the associations between single nucleotide polymorphisms (SNPs) in APOA1, APOA5 and APOB, and the risk of ischemic stroke in Chinese Han population." (PMID 28947988, 2017). "To date, several independent studies suggest that APOA1, APOA5 and APOB levels are risk factors for ischemic stroke risk in Western populations." (PMID 28947988, 2017). "Recent studies have identified several predisposing genes that are associated with ischemic stroke risk, including HDAC9, LTC4S, ALOX5, APOA1, APOB." (PMID 28947988, 2017). "The serum level of total APOA1-UP was independently correlated with the presence of ischemic stroke by multivariate logistic regression analysis (p < 0.0001)." (PMID 27043525, 2016). "Similar probability of ischemic stroke was found in men and women across all the three categories of APOA1-UP serum level." (PMID 27043525, 2016). "In addition, ApoE is a multifunctional protein that plays a key role in cholesterol metabolism; a higher level of APOA1 is considered to be protective against ischemic stroke, and taurocholic acid can lower postprandial lipemia." (PMID 37009888, 2023). "In addition, the associations with female sex, lipid-lowering drugs, BMI, ApoB/ApoA1 ratio, ApoA1, and ApoB were different for PD versus coronary events and PD versus ischemic stroke." (PMID 36008425, 2022). "Furthermore, in our study, we found that the ApoB/ApoA1 ratio and ethnicity had an additive interaction effect on first-ever ischaemic stroke (RERI 5.75, 95% CI 0.58 ~ 10.92)." (PMID 34082746, 2021). "Moreover, recent studies have identified several predisposing genes that are also corelated with an ischemic stroke risk, such as LTC4S, ALOX5, APOA1, APOB." (PMID 33808851, 2021). "However, a combination of APOC3 and APOA1 markers improved the differentiation between hemorrhagic and ischemic stroke." (PMID 31242583, 2019). "However, little is known about the contribution of APOA1, APOA5 and APOB genes polymorphisms to ischemic stroke risk, especially in the Chinese Han population." (PMID 28947988, 2017). "In several cross-sectional studies, higher serum levels of APOA1 and HDL-C were found in healthy subjects and considered as protective factors, whereas lower levels of APOA1 and HDL-C were associated with higher risks of the acute onset of ischemic stroke." (PMID 27043525, 2016). "Thus, a serum APOA1-UP level lower than 1.8301, or a positive APOA1-UP test result, was independently related to an increase of 188.13-fold in the probability of ischemic stroke, with a 95% CI of 38.04–930.43." (PMID 27043525, 2016). "The ApoB/ApoA1 ratio and cholesterol in medium size HDL were particularly of importance to understand the shared pathophysiology of CHD, HF and ischemic stroke and thus should be further investigated for the prevention of all three CVDs." (PMID 38724583, 2024). "Several recent studies noted that the lower HDL-C levels and increased ratio of the ApoA1/ApoB and serum TG, LDL-C, TC levels in smokers compared to non-smokers, all of these were related to the development of CAD and ischemic stroke." (PMID 31429711, 2019). "The height, weight, BMI, systolic blood pressure, glucose, pulse pressure, serum LDL-C, TG and TC levels were significantly lower; and serum HDL-C and ApoA1 levels, the ApoA1/ApoB ratio, and the proportion of drinkers were significantly higher in controls than in CAD and ischemic stroke patients." (PMID 31429711, 2019). "In all of the age strata, the probabilities of acute ischemic stroke changed in a similar trend as the APOA1-UP level increased, which suggest that age was not a confounding factor for the effect of APOA1-UP on ischemic stroke." (PMID 27043525, 2016). "In addition, we observed that ApoB, ApoA1, and their ratio had a significant difference for PD-coronary events but not PD-ischemic stroke." (PMID 36008425, 2022).
ischemic stroke (continued). "However, in the MR analysis adjusted for variables, the association between the ApoB/ApoA1 ratio and PAD, cerebrovascular diseases (including TIA and ischemic stroke), non-rheumatic valve diseases, atrial fibrillation and atrial flutter diseases were significantly weakened (all P>0.05)." (PMID 38310324, 2024). "Interestingly, our findings indicate that APOA1 is also not related to ischemic stroke subtypes." (PMID 31242583, 2019).
acute coronary syndrome (39 papers, 2005 to 2026). Signs and symptoms related to acute ischemia of the myocardium secondary to coronary artery disease. "Recent studies demonstrate that IgG autoantibodies against apolipoprotein A-1 (apoA-1) are raised in many diseases associated with a high cardiovascular risk, such as systemic lupus erythematosus, acute coronary syndrome, rheumatoid arthritis, severe carotid stenosis, and end-stage renal disease." (PMID 23227091, 2012). "HDL-apoA1-exchange was found to be lower from 16 acute coronary syndrome patients compared to 9 healthy control donors in a small human study, and this exchange was correlated with CEC, HDL-C, and apoA1 levels." (PMID 35052806, 2022). "We found a strong positive correlation of both Apo B and ApoB/ApoA1 in predicting high Gensini scores (scores ≥ 47) in patients who suffered from acute coronary syndromes (P value <0.001)." (PMID 33725226, 2021). "Further, it has been demonstrated that several apoA1 isoforms are present in plasma, and that at least some of these isoforms probably change during acute coronary syndrome." (PMID 21631938, 2011). "From this analogy it can easily be seen that if there is inadequate HDL-C or apoA-1 the atherogenic kitchen sink will overflow and result in acute coronary syndromes as happened in our case report." (PMID 15631632, 2005). "Several studies on patients with acute coronary syndrome have found that ApoA1 levels nonsignificantly and significantly decreased as the severity of CAD increased." (PMID 38921045, 2024). "The pooled results showed that HDL/apoA-1 replacement therapy use did not significantly decrease the percent atheroma volume (p = 0.766) or total atheroma volume (p = 0.510) in acute coronary syndrome (ACS) patients (N = 754)." (PMID 34422927, 2021). "The prevalence of antibodies against apolipoprotein A1 (anti-ApoA-1), the main component of HDL, is significantly higher in patients with acute coronary syndrome (21%) and in patients with SLE and/or antiphospholipid syndrome (13–32%), than in healthy subjects (1%)." (PMID 29670462, 2018).